GOT1L1 (glutamic-oxaloacetic transaminase 1 like 1)
Description:
Catalyzes the conversion of L-aspartate and 2-oxoglutarate to L-glutamate and oxaloacetate. It has been proposed to exhibit aspartate racemase activity, but this function remains debated and lacks strong experimental support.
Synonyms: MGC33309
Tractability: No criterion of Open Targets' tractability assessment is met for any kind of drug.
Gene: Protein-coding gene on chromosome 8 (37,934,281 to 37,940,124, reverse strand). Ensembl gene ENSG00000169154.
Subcellular location: Cytoplasm
Gene Ontology:
Molecular function: L-aspartate:2-oxoglutarate aminotransferase activity; protein binding; pyridoxal phosphate binding; transaminase activity
Biological process: aspartate biosynthetic process; amino acid metabolic process
Cellular component: cytosol; cytoplasm
Genetic constraint (gnomAD): Loss-of-function variants: 36 observed, 41.79 expected, observed/expected ratio (o/e) 0.86, 90% interval 0.66 to 1.14. The upper end of that interval is the gene's LOEUF score, 1.14, which puts it in group 4 of 6, group 1 being the genes least tolerant of losing a copy. Missense variants: 481 observed, 516.26 expected, observed/expected ratio (o/e) 0.93, 90% interval 0.86 to 1. Synonymous variants: 182 observed, 190.81 expected, observed/expected ratio (o/e) 0.95, 90% interval 0.84 to 1.08.
Homologues: Orthologues: chimpanzee GOT1L1 (96% identical), macaque GOT1L1 (93% identical), pig GOT1L1 (74% identical), mouse Got1l1 (71% identical), guinea pig GOT1L1 (66% identical), rat Got1l1 (65% identical), Drosophila melanogaster Got1 (36% identical), zebrafish got1l1 (36% identical), Caenorhabditis elegans got-1.2 (34% identical). Paralogues in human: GOT1 (39% identical), GOT2 (29% identical).
Diseases named in the same sentence as GOT1L1 in open-access papers:
GOT1L1 is named in the same sentence as 3 diseases in open-access papers, as found by Europe PMC text mining. Sharing a sentence is not in itself a finding about the gene and the disease. The quoted sentences say what the papers report.
breast carcinoma (1 paper, 2020). "Evaluation of the median mRNA expression of genes of the amplicon in TCGA breast cancer study discloses that a few genes (GOT1L1, ADRB3, STAR and LETM2) have a very low or no expression in breast cancers." (PMID 32987805, 2020).
GOT1L1 also shares sentences with these, for which no sentence is quoted: cancer (1 paper); malakoplakia (1).